SLC2A1 (solute carrier family 2 member 1)
Diseases named in the same sentence as SLC2A1 in open-access papers (continued):
Sharing a sentence is not in itself a finding about the gene and the disease.
tumor (continued). "The upregulated SLC2A1 (GLUT1) (T/TA = 9.49), HK2 (T/TA = 36.69), PFKP (T/TA = 15.97), PKM (T/TA = 4.08), and LDHA (T/TA = 8.58) suggested the increased of glucose utilization for lactate fermentation in ccRCC tumor vs. adjacent tissues." (PMID 35440542, 2022). "The results of qRT-PCR are consistent with those of bioinformatics analysis, meaning that SLC2A1 may be an oncogene in LUAD, while KLF4 may be a tumor suppressor gene." (PMID 35711943, 2022). "METTL3 can directly interact with the 5’-UTR or 3’-UTR region of HK-2 and the 3’-UTR region of glucose transporter SLC2A1 (namely GLUT1), which is dependent on IGF2BP2 or IGF2BP3 to stabilize gene expression, and activate the downstream glycolysis pathway to regulate tumor cell progression." (PMID 35022030, 2022). "SLC2A1, also named glucose transporter type 1 (GLUT1), could act as an oncogene to facilitate tumor development through the glycolysis pathway." (PMID 34992654, 2021). "The most likely explanation for the tumor essentiality of transporter protein genes SLC16A3, SLC2A1, and SLC2A8 is that tumor cells have an increased demand for nutrients and this demand is met by enhanced cellular entry of nutrients through upregulation of specific transporters." (PMID 33427197, 2021). "Using the integrated data of the tumor transcriptome from the TCGA database and the normal pancreas transcriptome from the Genotype-Tissue Expression (GTEx) database, we showed that LDHA, SLC2A1, and PGK1 were upregulated in tumor samples (logFC > 2, P < 0.05)." (PMID 33777046, 2021). "Among the hub genes, SLC2A1, CDH3 and EFHD2 displayed increased expression across the tumour stage." (PMID 34013637, 2021). "So far, we have proved that YTHDC1-induced miR-30d may function as a tumor suppressor gene by negatively regulating RUNX1 and its downstream glycolytic genes including HK1, and SLC2A1." (PMID 34021267, 2021). "Tumor tissue microarrays were stained for hypoxia-inducible factor-1α (HIF1A), solute carrier family 2 member 1 (SLC2A1, also known as glucose transporter 1 (GLUT1)), carbonic anhydrase 9 (CA9), and vascular endothelial growth factor A (VEGFA) and classified into low- or high-expression groups." (PMID 33810575, 2021). "Thus, not only HIF1A, but also VEGFA, SLC2A1, and CA9 allow the tumor cells to survive in hypoxic environments and are well-established markers of cellular hypoxia." (PMID 33810575, 2021). "Interestingly, several BBB-related transporters, including SLC2A1, ABCG2, ABCB1, SLCO1A2, and ATP10A were significantly decreased in ECs in tumor core." (PMID 34228647, 2021). "By inducing glycolysis-related genes products such as hexokinase 2 (HK2), lactate dehydrogenase A (LDHA), and glucose transporter 1 (GLUT1, also known as solute carrier family A1, SLC2A1), HIF-1α switches the glucose metabolism of hypoxic tumor cells to the glycolytic pathway." (PMID 35096814, 2021). "Tumor tissues with high c-Met expression level in TCGA have increased expression of H6PD, PDK2, PDK4, PDPR, PKLR, SLC2A2 genes whereas decreased expression of GYS1, HK1, HK2, SLC2A1, significantly." (PMID 34059694, 2021). "Expression for MMP3 (t = 4.884, p < 0.0001), SLC2A1 (t = 3.703, p = 0.0006), DDK3 (t = 3.981, p = 0.0003), POSTN (t = 2.061, p = 0.0455), RBP4 (t = 3.048, p = 0.004) and ASPN (t = 2.733, p = 0.0091) was confirmed to be higher in the tumor tissues." (PMID 32854182, 2020). "RNA-seq data also showed that THZ1 could diminish transcripts of MYC-targeted genes, such as HK2, CDC25A, GLUT1 (SLC2A1), PD-L1 (CD274), BRCA1, and BRCA2, which are important mediators of MYC’s function in tumor metabolism, immune evasion, and DNA repair." (PMID 32690037, 2020). "At the same time, LDHA, ADM, SLC2A1 and CA9 were also decreased in EP300 knockdown ESCC cells, indicating that EP300 may promote tumor growth and progress via hypoxia in ESCC." (PMID 31632486, 2019).
tumor (continued). "Likewise, CycT also strongly reduced the levels of pyruvate dehydrogenase (PDHA1) and glucose transporter SLC2A1 (GLUT1) in tumor cells." (PMID 30723259, 2019). "Also, we found higher transcript levels of SLC2A1 and HK2 in C-PDAC tumours relative to EL-PDAC tumours and the highest SLC2A3 transcript levels in QM-PDAC tumours." (PMID 30018740, 2018). "Besides, we showed that SLC2A1-over-expressing MGC-803 and MKN28 cells grew faster and larger tumor xenografts than control cells." (PMID 26193257, 2015). "Consequently, it can be inferred that the regulation of SLC2A1 expression in LUAD may influenced by DNA methylation mechanisms, subsequently contributing to tumor progression and prognosis." (PMID 40824962, 2025). "We found that Hif1a and Slc2a1 expression elevation in E0771 cells by stimulation with recombinant biglycan, which indicated that biglycan might mediate HIF1-α and Glut1 expression in tumor cells." (PMID 33966638, 2021). "We identified differential mRNA expression of the solute carrier family 2 member 1 (SLC2A1/GLUT1), matrix metallopeptidase 3 (MMP3) and nuclear factor erythroid 2–related factor 2 (NFE2L2/NRF2) genes in canine OSA tissue in comparison to paired non-tumor tissue." (PMID 34414229, 2021). "In our results, an inverse relationship between SLC2A1 in tumor cells and the PNI indirectly showed that glucose could not be transferred to normal cells for the maintenance of energy homeostasis or concentrated during cancer progression." (PMID 33735188, 2021). "It was previously shown that HIF-2α protein was gradually accumulated in tumor cells and contributed to the prolonged activation of hypoxia-related genes, in which HIF-2α regulated a glycolytic flux by targeting several glycolysis-related genes such as SLC2A1 and LDHA." (PMID 35096814, 2021). "Finally, glucose transporter 1 (GLUT1/SLC2A1), as a member of the GLUT family, is widely expressed in many types of cancer cells and plays a key role in glucose uptake for cancer cell metabolism to enable tumor cell growth and proliferation." (PMID 32855630, 2020). "While for SLC2A1 this could be explained by the functional support of the tumor cells with glucose, there is no explanation if PLS3 is functionally associated with tumor progression." (PMID 32599841, 2020). "The five independent prognostic genes were mainly expressed in cancer stem cells and epithelial cells, in particular, SLC2A1 and TFF2 were significantly high-expressed in epithelial cells in the tumor group than in nontumor group." (PMID 40662145, 2025). "Tumor regions without increased 18F-FDG uptake showed increased SLC13A5 and SLC16A1 expression, whereas tumors with increased 18F-FDG uptake showed high SLC2A1 and HIF1α." (PMID 35884416, 2022). "In addition, the five independent prognostic genes were mainly expressed in cancer stem cells and epithelial cells, in particular, the expressions of SLC2A1 and TFF2 in epithelial cells of tumor group were notably higher than those of nontumor group." (PMID 40662145, 2025). "According to the result of scRNA-seq analysis, the five prognostic SRRGs were mainly expressed in cancer stem cells and epithelial cells, in particular, the expressions of SLC2A1 and TFF2 in epithelial cells of tumor group were notably higher than nontumor group." (PMID 40662145, 2025). "Importantly, SLC2A1 co-stained with CK19 and was absent from alpha-smooth muscle actin (αSMA) positive stroma cells, suggesting that SLC2A1 is present predominantly in PDAC tumor cells." (PMID 35440539, 2022).
cancer (1,276 papers, 2002 to 2026). A tumor composed of atypical neoplastic, often pleomorphic cells that invade other tissues. "As a consequence, cancer cells require high levels of glucose uptake, and often upregulate glucose transporters such as GLUT1 (encoded by SLC2A1) to facilitate their high glucose requirements." (PMID 41547734, 2026). "A positive correlation was recognized between SLC2A1 expression and chemokines in numerous cancer types, with CCL7/26 and CXCL8 being primarily associated with LUAD." (PMID 40824962, 2025). "Univariate analysis confirmed SLC2A1 as a risk factor in several cancers, with hazard ratios of 1.666 for ACC, 1.935 for KICH, and 1.248 for LUAD." (PMID 40276602, 2025). "Results indicated a significant positive correlation between SLC2A1 and immunostimulants across most cancer types, with CD276 and PVR predominantly implicated in LUAD." (PMID 40824962, 2025). "The analysis showed that SLC2A1 is significantly associated with cancer-associated fibroblasts (CAFs) in several cancers, including ESCA, KIRC, LUAD, and TGCT." (PMID 40276602, 2025). "SLC2A1 (encoding glucose transporter GLTT1) plays a pivotal role in cancer metabolism through mediating the Warburg effect, a metabolic hallmark characterized by enhanced glucose uptake and preferential glycolytic flux in neoplastic cells." (PMID 40746529, 2025). "Individually, both SERPINE1 and the previously commented SLC2A1 have been widely associated to cancer." (PMID 41183125, 2025). "Inhibition of SLC2A1 is associated with increased apoptosis of cancer cells, suggesting a potential role in overcoming resistance to chemotherapeutic agents such as cisplatin." (PMID 40362545, 2025). "Among the HIF-1α target genes associated with migration and invasion of cancer cells, our microarray data showed that solute carrier family 2, facilitated glucose transporter member (SLC2A1) mRNA exhibited a significant increase in response to hypoxia." (PMID 39858431, 2024). "Glucose transporter 1 (GLUT1, encoded by SLC2A1), which is responsible for glucose uptake at the cell membrane in cancer cells, requires S-palmitoylation to maintain membrane localization and glucose import." (PMID 39284708, 2024). "SLC2A1 has been reported to be aberrantly expressed in several cancer types and is closely associated with the development and progression of human cancer." (PMID 36782138, 2023). "Together, these results establish that SMARCA4/2 loss directly reduces the transcription of SLC2A1, resulting in GLUT1 deficiency and subsequent impaired glucose uptake in these cancer cells." (PMID 37210563, 2023). "Second, using the EPIC algorithm, we found that SLC2A1 expression is positively correlated with cancer-associated fibroblasts (CAFs) in most cancers." (PMID 36358765, 2022). "SLC2A1 gene encodes GLUT1, which is a glucose transporter that mediates glucose metabolism in cancer cells." (PMID 35830566, 2022). "As pointed out above, the direction in which the variant allele shifts SLC2A1 expression varies from cancer to cancer." (PMID 34708297, 2022). "Genetic alterations in SLC2A1 were present in most cancers, and there were 80 mutation sites in SLC2A1, most of which were missense mutations." (PMID 36712872, 2022). "To explore the association between SLC2A1 expression and the clinicopathologic parameter of cancers, we performed differential analysis of SLC2A1 expression among different pathological stages of patients in pan-cancer." (PMID 36358765, 2022). "Several studies have pointed out the potential of the SLC transporter family in drug discovery, and SLC2A1 has been included as a key gene for diagnostic or prognostic cancer signature prediction in several cancers." (PMID 36712872, 2022). "To comprehensively explore the mechanism underlying SLC2A1 leading to the poor prognosis of cancer patients, we used LUAD as an example to perform GO, KEGG, and GSEA analyses." (PMID 36358765, 2022).
cancer (continued). "In a functional analysis, SLC2A1 was significantly associated with hypoxia, epithelial-mesenchymal transition, mTORC1 signaling, and multiple metabolic pathways in pan-cancer." (PMID 36712872, 2022). "In general, the results of the bioinformatics analyses implicated that ADAM9, MTHFD2, RRM2, and SLC2A1 are overexpressed in tumors and that the cumulative effect of their overexpression is associated with poor outcomes in multiple types of cancer." (PMID 33664854, 2021). "High SLC2A1 expression was associated with poor prognosis, cancer cell proliferation, decreased immune cells, including CD8 T cells and B cells which contributing to the death of gastric caner patients." (PMID 34116652, 2021). "High SLC2A1 expression was associated with poor prognosis, cancer cell proliferation, decreased immune cells, including CD8 T cells and B cells, and a low prognostic nutrition index, representing body nutrition-related status." (PMID 33735188, 2021). "The SLC2A1 gene encodes GLUT1, a glucose transporter that mediates a rate-limiting step for glucose metabolism in cancer cells." (PMID 31816603, 2019). "In general, cancer cells with acquired radioresistance exhibit higher expression of the glucose transporter GLUT-1 (encoded by SLC2A1) and enhanced lactate production levels than parental cells, which are maintained or increased upon radiation exposure." (PMID 27513864, 2016). "The results indicated that SLC2A1 may be linked to key cancer hallmarks, including the G2M checkpoint, glycolysis, the PI3K-AKT-mTOR pathway, and epithelial-mesenchymal transition (EMT)." (PMID 40276602, 2025). "Notably, SLC2A1, which encodes the major glucose transporter 1 (GLUT1) The Cancer Genome Atlas (TCGA) and plays a crucial role in the glycolytic pathway, was enriched in the Glucagon signaling pathway." (PMID 40278414, 2025). "In summary, SLC2A1 is linked to poor prognosis in various cancers, especially LUAD, where it may serve as a prognostic biomarker." (PMID 40276602, 2025). "Concurrently, safety-aware designs should address hepatic monitoring for FAO inhibitors (etomoxir elevates liver triglycerides by 40%); cancer risk stratification for NAD+ boosters in SLC2A1 variant carriers; and immunosuppression screening for fecal transplants." (PMID 41184254, 2025). "Increased SLC2A1 expression has been associated with poor survival outcomes in various cancers." (PMID 39858431, 2024). "Furthermore, a highly metabolically active metabolic cancer-associated fibroblast defined by the expression of SLC2A1, a membrane glucose transporter, was described." (PMID 39796089, 2024). "The high expression of SLC2A1 in cancers is often associated with poor prognosis." (PMID 36358765, 2022). "For example, GLUT1 (SLC2A1) is the primary glucose transporter implicated in tumorigenic transformation and is frequently considered a general therapeutic target in many advanced cancers." (PMID 36358940, 2022). "The correlation analysis between SLC2A1 and the enrichment scores of 50 HALLMARK pathways across TCGA cancers showed that SLC2A1 was significantly positively correlated with MTORC1_SIGNALING, HYPOXIA, EPITHELIAL_MESENCHYMAL_TRANSITION, and ALLOGRAFT_REJECTION in almost all cancers." (PMID 36712872, 2022). "SLC2A1 might serve as a novel pan-cancer diagnostic and prognostic biomarker and provide an opportunity to develop new immunotherapy strategies." (PMID 36358765, 2022). "Therefore, to explore the cause of the high expression level of SLC2A1 in cancers, we analyzed DNA promoter methylation and RNA methylation." (PMID 36358765, 2022). "We evaluated the diagnostic value of SLC2A1 in pan-cancer by using ROC curves." (PMID 36358765, 2022). "Although we found that SLC2A1 is highly expressed in cancers compared with in normal tissues, whether SLC2A1 has diagnostic value for cancers still need further analysis." (PMID 36358765, 2022). "At the same time, SLC2A1 was a risk factor in these cancers." (PMID 36712872, 2022).
cancer (continued). "Therefore, authors suggest that SLC2A1 is involved in ccRCC, increasing the susceptibility to the development of cancer however, its role is unclear." (PMID 28854935, 2017). "It is hypothesized that the cytotoxic effect of methylglyoxal in cancer cells will be promoted by a synergistic effect of the up-regulation of SLC2A1 gene and the down-regulation of genes encoding enzymes that are involved in the degradation of methylglyoxal." (PMID 27635343, 2016). "Notably, large-scale mapping of cancer dependencies showed that FGFR2-fusion+ ICC cells have significantly enriched dependency on SLC2A1 (encoding GLUT1, the high-affinity glucose transporter) relative to other cancer cell lines, consistent with a particularly high demand for glucose at baseline." (PMID 38714664, 2024). "However, SLC2A1/2 was associated with short OS in HNSCC cancer patients." (PMID 37542344, 2023). "Interestingly, oncogenic KRAS mutations were shown to increase glucose uptake in cancer cells and lactate production through upregulation of glycolytic genes encoding glucose transporter SLC2A1/GLUT1 and the monocarboxylate transporters SLC16A1/MCT1, SLC16A7/MCT2, and SLC16A3/MCT4." (PMID 34003553, 2021). "SLC2A1 overexpression, in turn, contributes to the Warburg effect, a characteristic metabolic reprogramming in cancer cells." (PMID 40746529, 2025). "While the specific hsa-miR-378c - SERPINE1 interaction has not been associated with cancer, the hsa-miR-378a version of hsa-miR-378c has been directly related with SLC2A1 in cancer contexts." (PMID 41183125, 2025). "SLC2A1, also named GLUT1, is a membrane protein facilitating glucose uptake in most cell types, including cancer cells." (PMID 41473324, 2025). "HIF-1 induces the expression of solute carrier family 2 member 1 (SLC2A1) and solute carrier family 2 member 3 (SLC2A3), which encode GLUT1 and GLUT3, respectively, to promote glucose uptake to meet the demand of glucose for the growth of hypoxic cancer cells." (PMID 39858016, 2025). "For example, elevated SLC2A1 (GLUT1) and SLC2A3 (GLUT3), which facilitate the transport of glucose across the plasmatic membrane, have been associated with increased cancer metabolism." (PMID 40141095, 2025). "The overexpression of SLC2A1 in various types of cancer, including breast, lung, liver, endometrial, oral, Colorectal and gastric cancers, is particularly intriguing." (PMID 40746529, 2025). "This family contains fourteen members including GLUT1 encoded by the SLC2A1 gene, which plays a significant role in the development of cancer." (PMID 40083702, 2025). "This study showed that SLC2A1 is overexpressed in LUAD compared to normal lung tissues, and this overexpression was linked to a poorer cancer prognosis." (PMID 40563443, 2025). "Mechanistically, SLC2A1 is thought to be a key player in cancer cell proliferation and metastasis through multiple pathways." (PMID 40746529, 2025). "As a target gene of miR-132-3P, SLC2A1 (GLUT1) is crucial for maintaining cellular energy supply and is closely associated with cancer prognosis." (PMID 39981435, 2025). "SLC2A1 exhibited a significant upregulation in cancer tissues in comparison to normal tissues (P < 0.001)." (PMID 40824962, 2025). "Previous studies have consistently shown aberrant expression of SLC2A1 in numerous cancers and that it is related to poor prognosis." (PMID 39526479, 2024). "Glucose transporter 1 (GLUT1), a single transporter protein encoded by the SLC2A1 gene, promotes glucose uptake and enhances glycolysis in cancer cells." (PMID 39858431, 2024). "This uptake of glucose is mainly facilitated by the increased expression of GLUT1 (SLC2A1) in various cancer cells." (PMID 38399253, 2024). "Inactivating SLC2A1 or LDHA affects the glycolytic pathway of cancer cells, ultimately leading to apoptosis in vitro and in vivo." (PMID 38555429, 2024).